CASP9 (caspase 9)
Diseases named in the same sentence as CASP9 in open-access papers (continued):
Sharing a sentence is not in itself a finding about the gene and the disease.
microphthalmia (2 papers, 2013 to 2019). Congenital or developmental anomaly in which the eyeballs are abnormally small. "Previously identified mitochondrial proteins associated with the development of microphthalmia, namely HCCS and COX7B, were shown to induce a reactive oxygen species (ROS)‐dependent induction of caspase 9‐mediated cell death." (PMID 30389680, 2019).
myocardial inflammation (2 papers, 2015 to 2022). "Chronic myocardial inflammation subsequently affects mitochondria and induces significant release of Hsp60 and caspase-9, −8 and −3, suggesting activation of both apoptotic pathways with stronger implication on the intrinsic pathway." (PMID 25888309, 2015).
periodontitis (2 papers, 2019 to 2021). An acute or chronic inflammatory process that affects the tissues that surround and support the teeth. "Since SOD2 and BIRC3 can inhibit apoptosis, we additionally investigated the levels of the apoptotic markers CASP3 and CASP9 in gingival biopsies from periodontally healthy and periodontitis subjects." (PMID 33435582, 2021). "SOD2, BIRC3, and the apoptotic markers caspases 3 (CASP3) and 9 (CASP9) were analyzed in gingiva from periodontally healthy and periodontitis subjects by real-time PCR and immunohistochemistry." (PMID 33435582, 2021). "These transcriptional results were further confirmed at the protein level by immunohistochemistry, i.e., more pronounced immunostaining for active CASP3 and CASP9 was found in gingiva from periodontitis patients in comparison to periodontally healthy gingiva." (PMID 33435582, 2021). "As analyzed by quantitative real-time PCR, both CASP3 and CASP9 were significantly (p < 0.05) increased in gingival samples from periodontitis patients as compared to gingival biopsies from periodontally healthy individuals." (PMID 33435582, 2021). "Moreover, our transcriptional and protein analyses showed elevated levels of the apoptotic markers CASP3 and CASP9 in gingiva from periodontitis patients in comparison to periodontally healthy gingiva, indicating increased apoptotic activity at sites of periodontitis." (PMID 33435582, 2021). "Gingiva from periodontitis patients showed significantly higher SOD2, BIRC3, CASP3, and CASP9 levels than periodontally healthy gingiva." (PMID 33435582, 2021). "In conclusion, P. gingivalis HmuY protein might contribute to the survival of PBMC in periodontitis by regulating the transcriptional profile of genes involved in apoptosis, such as FASL, caspase 9, APAF1, FAS, TNFSF10 (TRAIL), and BAK1." (PMID 31011284, 2019).
prostate tumor (2 papers, 2014). "In order to further illuminate the mechanism of MRV induced apoptosis in hypoxic prostate tumor cells, we determined the activation status of caspase 8 and caspase 9 in MRV-infected hypoxic DU145 cells." (PMID 24504474, 2014).
Retinal atrophy (2 papers, 2023 to 2024). A nonspecific term denoting wasting, especially as a result of degeneration, of the retinal pigment epithelium (RPE) and neurosensory retinal cells. "Moreover, inhibiting caspase-9 increased the reduction of retinal edema twice as much as anti-VEGF drugs, and only the neutralisation of caspase-9 reduced retinal atrophy, indicating neuroprotection." (PMID 38999513, 2024). "Caspase-9 inhibition reduced retinal atrophy and preserved ERG response; VEGF neutralization did not prevent neurodegeneration following RVO." (PMID 37449272, 2023).
retinal ischemia (2 papers, 2020 to 2023). A ischemic disease that involves the retina. "Using an integrated panel of ophthalmic imaging readouts, we evaluated the progression of retinal ischemia, edema, and neurodegeneration in wild-type mice treated with either a VEGF-neutralizing antibody or a topical caspase-9 inhibitor." (PMID 37449272, 2023).
sarcopenia (2 papers, 2020 to 2021). Progressive decline in muscle mass due to aging which results in decreased functional capacity of muscles. "As expected, two caspases, caspase-3 and caspase-9, were activated in all three sarcopenia samples." (PMID 32226296, 2020). "Compared with the HF group, the expression levels of cleaved caspase-9, cleaved caspase-3, and BAX in the HF + sarcopenia group were significantly increased (P < 0.0001), but BCL2 did not change significantly (P > 0.05)." (PMID 35126176, 2021).
steatosis (2 papers, 2019). Increased lipid within the cytoplasm of cells. "Both steatosis and NAFLD were associated with Casp9, and described as a potential marker for hepatocyte apoptosis during the development of NAFLD21." (PMID 31506438, 2019). "Compared to the alcohol-treated WT mice, mice with genetic ablation of NR4A1 exhibited attenuation of hepatocyte vacuolation, fibrosis, steatosis, and caspase-9-related mitochondrial apoptosis induced by alcohol treatment." (PMID 31839999, 2019).
T-cell leukemia (2 papers, 2022 to 2024). A malignant disease of the T-lymphocytes in the bone marrow, thymus, and/or blood. "We next characterized caspase-9-independent cell death mechanisms downstream of mitochondrial disruption using a caspase-9-deficient human T cell leukemia Jurkat cell line, JMR." (PMID 36231015, 2022).
T-cell Lymphoma (2 papers, 2015 to 2024). "Again, the potential clinical relevance of these observations is shown by the similarly increased phosphorylation of histone 2AX and cleavage of PARP1, caspase 3 and caspase 9 in the T-cell lymphoma patient cell sample exposed to romidepsin." (PMID 26473529, 2015). "In addition, tests on the T-cell Lymphoma Cell Line CCRF-CEM showed induction of arrest in the S phase and apoptosis through increased expression of Bax, caspase-9, and cascade." (PMID 38474594, 2024).
testicular cancer (2 papers, 2014 to 2020). A primary or metastatic malignant neoplasm that affects the testis. "Re-expressing CMTM3 also markedly promoted caspase-9 protein expression in testicular cancer cells." (PMID 24586462, 2014).
thymic carcinoma (2 papers, 2012 to 2020). Thymic carcinoma (TC) is a type of thymic epithelial neoplasm characterized by a high malignant potential. "We further found a relationship between BPAs and degree of malignancy for four markers, namely Bax, p73, Casp-9 and Bcl-2, included 176 thymoma patients and 36 thymic carcinoma patients, and BPAs were significantly correlated with thymic carcinoma (P = 0.010)." (PMID 32993581, 2020). "Four markers, namely Bax, p73, Casp-9 and Bcl-2, from two articles that included 176 cases of thymoma and 36 cases of thymic carcinoma were selected." (PMID 32993581, 2020). "Caspase-9 presented a lower expression in type B thymoma and thymic carcinoma than in type A and metaplastic thymoma, which was consistent with previous research." (PMID 22974165, 2012). "The decreasing tendency of Caspase-9 transcription and translation indicated that the interruption of Caspase-9 related apoptosis signaling pathways might promote the generation of type B thymoma and thymic carcinoma." (PMID 22974165, 2012). "In addition, Caspase-9 expression was relative lower in type B thymoma and thymic carcinoma." (PMID 22974165, 2012). "Unlike type A thymoma, the expression of Casp-9 was relatively lower in type B thymoma and thymic carcinomas." (PMID 22974165, 2012).
thymic epithelial neoplasm (2 papers, 2012 to 2014). An epithelial neoplasm that affects the thymus gland. "Recent study has demonstrated that the overexpression of c-Jun, p73 and Caspase-9 in thymic epithelial tumors is closely related with the pathogenesis and biological behavior of the neoplasms." (PMID 24444077, 2014). "In our project, 30 out of 60 (50%) thymic epithelial neoplasms have positive Caspase-9 expression, which was slightly lower than the Caspase-9 expression in normal control tissues (7/11, 63.6%)." (PMID 22974165, 2012). "The overexpression of c-Jun, p73 and Casp-9 in thymic epithelial tumors is closely related with the pathogenesis and biological behavior of the neoplasms." (PMID 22974165, 2012). "In this study, we analyzed the expression of four chromosome 1-related genes, namely c-Jun, p73, Casp-9 and N-ras, in 60 cases of thymic epithelial tumors." (PMID 22974165, 2012).
thymoma (2 papers, 2012 to 2020). A neoplasm arising from the epithelial cells of the thymus. "In different subtype, the expression of Caspase-9 in thymic epithelium tumors mainly existed in thymomas constructed by bland epithelial cells, including type A and metaplastic thymoma." (PMID 22974165, 2012).
Type 1 diabetes (2 papers, 2010 to 2023). "Another example is CASP9 (MIM, 602234), which participates the immune attack in a murine model of type 1 diabetes." (PMID 20808825, 2010).
abscesses (1 paper, 2023). "Compared to Casp9fl/fl mice, abscess numbers in kidneys and livers of infected Casp9fl/fl Tie2-Cre+ mice were clearly reduced suggesting that caspase-9 activity affects staphylococcal abscess formation." (PMID 38157331, 2023). "Specifically, we asked whether S. aureus may deploy AdsA and derived death-effector deoxyribonucleosides to trigger assembly of the apoptosome and coupled processing of pro-caspase-9 in phagocytes that are recruited to abscesses." (PMID 38157331, 2023). "Intriguingly, most abscess margin-positioned F4/80-positive macrophages co-localized with signals specific for cleaved (activated) caspase-9 indicating that wild-type staphylococci preferentially provoke induction of intrinsic apoptosis in phagocytes during infection." (PMID 38157331, 2023). "Moreover, infection with the adsA-deficient strain phenocopied lack of caspase-9, which is in agreement with the notion that AdsA essentially contributes to the development of infectious foci and staphylococcal survival within deep-seated abscesses." (PMID 38157331, 2023). "The analysis revealed that lack of adsA in S. aureus phenocopied the Casp9 mutation in the host as adsA mutant-derived abscesses were also characterized by infiltrates of F4/80-positive phagocytes, irrespectively of whether animals expressed the Tie2-driven Cre recombinase or not." (PMID 38157331, 2023).
acute liver failure (1 paper, 2019). Rapid deterioration of liver function causing encephalopathy and coagulopathy. "TNFα was considered to play a role in hepatocytes apoptosis and liver injury and further triggered Bax activation and cleavage of caspase-9 and caspase-3 in acute liver failure (ALF)." (PMID 31921708, 2019).
Atrophy (1 paper, 2017). Any weakening or degeneration, especially through lack of use. "Firstly, by controlling the expression of MAFbx/atrogin-1 and MurF1 in the early phase of atrophy development as demonstrated by others and secondly by controlling the expression of APAF-1/Caspase 9 in the late phase of atrophy development as proposed in our study." (PMID 28493972, 2017). "Therefore, we propose that in addition to the role of miRNA-23a in the early stage of atrophy, the downregulation of miRNA-23a in the late development phase of this disease might also play a significant role by modulating the miRNA-23a/APAF-1/Caspase 9 axis of regulation." (PMID 28493972, 2017).
breast invasive carcinoma (1 paper, 2024). "The analysis of the clinical stages of patients with breast invasive carcinoma indicated that the BAX, BCL2L1, CASP8, CASP9, RELA, and NFKBIA gene expression levels were higher in stages 3 and 4 for all BRCA patients, and in stage 4 for BRCA-LumA patients, than in other clinical stages." (PMID 38542508, 2024).
cardiac arrest (1 paper, 2021). Cessation of breathing and/or cardiac function. "At 5 hours after cardiac arrest, comparison between just two groups by t-test showed significantly reduced caspase-9 activity of the hypothermia group compared to the normothermia group regardless of region (hippocampus, p = 0.048; cerebellar vermis, p = 0.049)." (PMID 34138955, 2021).
chlamydial infection (1 paper, 2015). "Our results suggest that the ratio of Apaf-1 and caspase-9 influences host susceptibility to chlamydial infection." (PMID 26290316, 2015). "In an opposite manner, human and mouse cells treated with a caspase-9 inhibitor and caspase-9−/− MEFs are more insusceptible to chlamydial infections than control cells." (PMID 26290316, 2015). "These opposition contributions to the chlamydial infection were confirmed using caspase-9−/− and apaf-1−/− MEFs." (PMID 26290316, 2015). "Caspase-9 is generally activated in apoptosomes that contain Apaf-1, but the C9-i used here, which is an antagonist of caspase-9 self-cleavage, inhibited chlamydial infection." (PMID 26290316, 2015). "Interestingly, caspase-9 was activated in Apaf-1−/− MEFs by chlamydial infection, but the activated caspase-9 was disconnected from the caspase cascade that activates caspase-3." (PMID 26290316, 2015). "There data suggest the hypothesis that chlamydial infection-mediated repression of apoptosis is at least partially a result of caspase-9 sequestration in inclusions, in which caspase-9 is precluded from its role (or availability) in the host apoptosis cascade." (PMID 26290316, 2015). "Based on the results shown here, two hypotheses are proposed regarding an epistatic effect of apaf-1 and caspase-9 on chlamydial infection." (PMID 26290316, 2015). "That is, caspase-9 sequestration by chlamydial infection from the host apoptosis cascade results in apoptosis repression of host cells, and Apaf-1 may compete against chlamydial utilization of caspase-9." (PMID 26290316, 2015). "Thus, it is possible that caspase-9 activation is required for chlamydial infection." (PMID 26290316, 2015). "Interestingly, caspase-9 in apaf-1−/− MEFs was activated by chlamydial infection but during the infection caspase-3 was not activated." (PMID 26290316, 2015).
cholesteatoma (1 paper, 2015). A pathologic process characterized by the proliferation of keratinizing squamous epithelium resulting in the accumulation of keratin and cells in the middle ear and/or mastoid. "NOD1 and many proapoptotic caspase genes such as CASP1, CASP2, CASP8, and CASP9 were not altered in cholesteatoma." (PMID 25922834, 2015).
chromophobe carcinoma (1 paper, 2003). "Likewise, the loss of caspase-9 expression in chromophobe carcinoma may contribute to the rise of this type of tumour, but more data are obviously needed to confirm this initial finding." (PMID 14647151, 2003).
chronic heart failure (1 paper, 2021). "On the one hand, tanshinone IIA regulates the expression of Caspase-9, CTGF, and RhoA protein levels by upregulating the level of miR-133 and exerting antimyocardial weight on chronic heart failure rats." (PMID 33763149, 2021).
cognitive decline (1 paper, 2025). "The inclusion of features like CASP9, LCK, and MMSE, highlighted by SHAP analysis, supports early prediction by capturing processes associated with apoptosis, neuroinflammation, and cognitive decline, respectively." (PMID 40228177, 2025).
edema (1 paper, 2022). An abnormal accumulation of fluid beneath the skin, or in one or more cavities of the body. "We previously found that inhibition of caspase-9 or ablation of EC Casp9 protected from retinal edema at early points P-RVO." (PMID 36347836, 2022).
embryonal carcinoma (1 paper, 2015). A non-seminomatous malignant germ cell tumor characterized by the presence of large germ cells with abundant cytoplasm resembling epithelial cells, geographic necrosis, high mitotic activity, and pseudoglandular and pseudopapillary structures formation. "Our results are in accordance with former findings demonstrating that in P19 embryonal carcinoma cells, RA and BMP-4 induce the activation of caspase-9, being upstream of caspase-3 in the RA/BMP-4 mediated apoptosis enzyme cascade." (PMID 26173116, 2015).
emotional dysregulation (1 paper, 2025). "Reduced neurotrophic support (IGF-1), heightened apoptotic and oxidative signaling (CASP-9 and nNOS), and deficient anti-inflammatory control (IL-10) jointly foster neuronal instability and emotional dysregulation." (PMID 41150816, 2025).
endophthalmitis (1 paper, 2016). An infectious process affecting the internal structures of the eye. "Together, these findings imply the involvement of caspase-9 and -3 activation and PARP-1 cleavage in executing the retinal cell death in endophthalmitis." (PMID 27551524, 2016).
endotoxemia (1 paper, 2012). "We have found that endotoxemia in the sucking animals evoked by increasing doses of LPS caused dose-dependently upregulation of pro-apoptotic caspase-9 and executioner caspase-3 protein level in the pancreatic acini incubated with caerulein." (PMID 22685683, 2012). "Endotoxemia in the newborn rats due to increasing doses of LPS (5, 10 or 15 mg/kg/day × 5 days) was stimulatory factor for caspase-9 expression." (PMID 22685683, 2012). "The aim of this study was to investigate in the pancreatic acinar cells isolated from adult animals, the effects of foregoing infant rats endotoxemia on TLR4, HSP60 and pro-apoptotic Bax, caspase-9 and -3 or antiapoptotic Bcl-2 protein expression." (PMID 22685683, 2012).
epithelioid mesothelioma (1 paper, 2016). "In two epithelioid mesothelioma cell lines, down-regulation of calretinin by a lentiviral short hairpin approach impaired cell proliferation and triggered apoptosis via the intrinsic caspase-9-dependent pathway suggesting that calretinin is important for epithelioid mesothelioma cell survival." (PMID 26848772, 2016).
erythroleukemia (1 paper, 2023). Acute erythroid leukemia characterised by the presence of at least 50% erythroid precursors and at least 20% myeloblasts in the bone marrow. "Thus, SFP 2205 may stimulate apoptosis by suppressing the PI3K/AKT/Bad/Bcl-xL/Caspase-9/Caspase-3 signaling pathway in erythroleukemia cells." (PMID 37233483, 2023).
eye cancer (1 paper, 2022). "BPA intoxication increases the level of apoptotic proteins, including caspase-9, in the eye of rats, which suggests an increased risk of developing eye cancer following eye trauma." (PMID 36362630, 2022).
fungal infection (1 paper, 2023). "Our data indicate that a similar protein, demonstrating higher activity towards apoptosis and fungal infection, is also present in G. mellonella; however, more detailed research is needed to compare the structure and physiology of detected protein with mammalian caspase-9." (PMID 37373316, 2023).
gallbladder tumor (1 paper, 2014). "To determine whether the impact of oridonin on tumor growth inhibition was related to caspase-3, caspase-9, NF-κB, Bax, Bcl-2, PARP-1 and cytochrome c, we evaluated the levels of these apoptosis-related proteins in the gallbladder tumor tissues by western blot analysis." (PMID 24655726, 2014).
gastric ulcer (1 paper, 2025). An ulcerated lesion in the mucosal surface of the stomach. "The CHRs pretreatment clearly down-regulated the expression of Caspase 3 and Caspase 9 in mice with ethanol-induced gastric ulcers." (PMID 40283949, 2025).
Giardia infections (1 paper, 2023). "In addition, like HSP70, TLR4 could also mediate inhibition of CASP-9 and CASP-8 activation, expanding the HSP70-mediated anti-apoptotic signaling network during Giardia infections." (PMID 36937289, 2023).
hemoglobinopathies (1 paper, 2025). "There are two different approaches for gene therapy of hemoglobinopathies, one based on gene addition or gene silencing using lentiviruses as vectors and the other based on gene editing strategies using CRISPR-Caspase 9 technology or base editing." (PMID 41463103, 2025).
hemorrhage (1 paper, 2023). Loss of blood from the vascular compartment to the exterior or into nonvascular body space as a result of rupture or severance of the blood vessels. "The phenotypes observed in Casp9–/– mice are associated with reduced neuronal apoptosis, accumulation of necrotic tissues in the brain, and frequent intracerebral hemorrhages, highlighting the importance of CASP9 in brain development." (PMID 37612410, 2023).